PIK3R5 (phosphoinositide-3-kinase regulatory subunit 5)
Diseases named in the same sentence as PIK3R5 in open-access papers:
PIK3R5 is named in the same sentence as 45 diseases in open-access papers, as found by Europe PMC text mining. Sharing a sentence is not in itself a finding about the gene and the disease. The quoted sentences say what the papers report.
melanoma (5 papers, 2012 to 2025). A malignant, usually aggressive tumor composed of atypical, neoplastic melanocytes. "Recent studies in melanoma have indicated that some components of the PI3K pathway (PTEN, MTOR, IRS4, PIK3R1, PIK3R4, PIK3R5 and NFKB1) are co-mutated in 17% of BRAF V600E mutant and 9% of NRAS mutant melanomas." (PMID 23006971, 2012). "PIK3CG mutation and amplification are frequent in multiple malignancies, including 9–11% of melanomas and uterine, stomach and squamous cell lung cancers, while genetic alterations in PIK3R5 and PIK3R6 are prevalent in uterine cancer and melanoma, occurring in 4–8% of cases." (PMID 32630372, 2020). "PIK3R5 and PLAT positively regulated cancer metastasis and EMT of osteosarcoma cells and melanoma, respectively, while little is known about their roles in EOC metastasis." (PMID 35538537, 2022).
breast carcinoma (4 papers, 2016 to 2024). "Here, EVs from eribulin-breast cancer cells contained higher levels of PIK3R5 (log2FC = +3.877), PIK3C2B (log2FC = +1.664) and PIK3R1 (log2FC = +1.500) mRNAs than controls." (PMID 38534323, 2024). "PIK3R5 gene has predictive potential for lymph node metastasis in breast cancer, while PSEN1 downregulation promotes the chemoradiotherapy resistance of esophageal carcinoma." (PMID 35480305, 2022). "Mutation of PIK3R5 and other genes (i.e. PRKCZ, PTEN, RHEB and RPS6KB1) have altered PI3K signaling pathway, which is the central pathway for both colorectal and breast cancers." (PMID 27161113, 2016).
leukemia (3 papers, 2012 to 2024). A malignant (clonal) hematologic disorder, involving hematopoietic stem cells and characterized by the presence of primitive or atypical myeloid or lymphoid cells in the bone marrow and the blood. "PIK3R5 and PIK3CG, which encode a p101 regulatory and p110 catalytic subunit of PI3Kγ complex, are essential for the survival of a leukemia subset including blastic plasmacytoid dendritic cell neoplasm (BPDCN) and AMLs with high expression of PIK3R5 via a genome-wide CRISPR interference screening." (PMID 39507412, 2024). "This led to the discovery of four G protein-coupled purinergic receptors that are elevated in cytarabine-resistant PIK3R5-low leukemia cells and stimulate PI3Kγ-PAK1 signaling that contributes to eganelisib sensitivity." (PMID 39507412, 2024). "surprisingly found that eganelisib not only considerably extends the survival time of mice bearing PIK3R5-high leukemia PDX but also resensitizes those with low PIK3R5 to cytarabine." (PMID 39507412, 2024). "Additional assays are required to examine whether SPI1 is related to elevated PIK3R5 in this leukemia subset." (PMID 39507412, 2024). "Indeed, PIK3R5 is induced in PIK3R5-low leukemia cells by Toll-like receptor agonist and inflammatory cytokines, such as interferon α (IFNα) and IFNγ." (PMID 39507412, 2024). "Such a regulation renders leukemia PDXs sensitive to the PI3Kγ inhibitor eganelisib, indicating a leukemia subset selectively addicted to PI3Kγ signaling potentially driven by innate inflammatory signaling and elevated PIK3R5." (PMID 39507412, 2024). "Interestingly, the PIK3R5-high leukemia subset does not associate with specific mutational profiles but shows a molecular signature of innate immune response." (PMID 39507412, 2024). "Further analysis suggests a dependency of PIK3R5 and PIK3CG exclusively in leukemia cells and confirms an expression pattern of PIK3R5 and PIK3CG specifically enriched in BPDCN and a subset of AML compared with most AML cell lines." (PMID 39507412, 2024). "While sufficient evidence confirms the regulation of PIK3R5 by SPI1, it is still unclear whether the observed SPI1-PIK3R5 axis occurs in the leukemia subset defined by elevated PIK3R5." (PMID 39507412, 2024). "Furthermore, we confirmed the overexpressed PIK3R5, DGKQ and TNFSF9, which are crucial components of kinase pathways involved in leukemia and lymphoma, in manipulated Jurkat samples." (PMID 27681508, 2016).
lung carcinoma (3 papers, 2013 to 2022). "Among 63 gene members, phosphatidylinositol 3-kinase (PIK3R5), phospholipase C (PLCG2), and SHC adaptor protein showed strong associations with lung cancer susceptibility in our GWAS." (PMID 23762359, 2013).
osteosarcoma (3 papers, 2020 to 2022). A usually aggressive malignant bone-forming mesenchymal neoplasm, predominantly affecting adolescents and young adults. "However, in stark contrast, miR-210 increases cell proliferation in human osteosarcoma cell lines by modulating the Akt-mTOR signaling pathway by directly silencing PIK3R5 (phosphoinositide-3-kinase regulatory subunit 5) expression through directly targeting the PIK3R5 3′UTR." (PMID 35052722, 2021).
ovarian carcinoma (3 papers, 2019 to 2025). A malignant neoplasm originating from the surface ovarian epithelium. "PIK3R5 plays an important role in cell growth and cell motility and has been found to be overexpressed in ovarian cancer that shows high levels of chemoresistance, which is a common feature in PDAC." (PMID 40728119, 2025). "CD83 highly-associated genes, such as ITGAM, IL1B, CYBB, PIK3R5, BTK, and OSM, ectopically express in ovarian cancer cells or tissues, involving in ovarian cancer progression, hypoxia networks, and the development of chemoresistance." (PMID 32823589, 2020).
diabetes (2 papers, 2021). "Interestingly, most transcripts namely, Pck2, Prkab2, Pik3r1, Foxo1, Irs1 and Pik3r5 are commonly involved in these pathways and this suggests a significant involvement and contribution of these genes in aberrant skeletal muscle metabolism during diabetes." (PMID 34190986, 2021).
esophageal cancer (2 papers, 2019 to 2022). A primary or metastatic malignant neoplasm involving the esophagus. "Not all such identified proteins are lowly expressed in esophageal cancer, except for protein phosphoinositide 3-kinase regulatory subunit 5, validating the efficacy, and accuracy of our prediction." (PMID 31850330, 2019).
Hepatic fibrosis (2 papers, 2023 to 2025). The presence of excessive fibrous connective tissue in the liver. "Our data unveils a lnc-Helf/PTBP1/PIK3R5/AKT feedforward amplifying signaling to exacerbate the process of hepatic fibrosis and inflammation, thus providing a possible therapeutic strategy for hepatic fibrosis." (PMID 37805473, 2023). "Our results unveil a lnc-Helf/PTBP1/PIK3R5/AKT feedforward, amplifying signaling that exacerbates the process of hepatic inflammation and fibrosis, thus providing a possible therapeutic strategy for hepatic fibrosis." (PMID 37805473, 2023).
prostate carcinoma (2 papers, 2020 to 2023). A carcinoma that arises from epithelial cells of the prostate gland. "PIK3R5, TBX2 and TWIST1 gene were found to be hypermethylated in all four cancers, while CDKN2A (ARF) is hypermethylated in colorectal and prostate cancers." (PMID 33143142, 2020).
Sepsis (2 papers, 2022 to 2024). Sepsis is defined as life-threatening organ dysfunction caused by a dysregulated host response to infection. "Other transcripts upregulated in CD5L− peritoneal cells, including Osm, Il18bp, Ripk1, Nub1, Tlr2, Stat1, Irf1, Nfkb1, Pik3r5, or their coding proteins, were already associated with sepsis severity." (PMID 38750020, 2024). "Among 5,607 DEGs, Lrg1, Ace2, Itgb6, Hmgb2, Pik3r5, Itgam, Plcb1, Jak2, Vegfa, and Hif1α were associated with the entire course of sepsis-induced myocardial injury, which have been reported previously." (PMID 35721566, 2022). "Thus, our results suggest that Pik3r5 may serve as a key mediator in sepsis-induced myocardial injury." (PMID 35721566, 2022). "Moreover, Pik3r5 was located in the center of the gene co-expression network, and may play an important role in the progression of sepsis-induced cardiac injury." (PMID 35721566, 2022). "Moreover, we identified that Pik3r1 and Pik3r5 were at the center of the gene co-expression network, and inhibition of PI3Kγ activity had a cardioprotective role in CLP-induced sepsis." (PMID 35721566, 2022).
acute lymphoblastic leukemia (1 paper, 2023). Leukemia with an acute onset, characterized by the presence of lymphoblasts in the bone marrow and the peripheral blood. "Suppressed interferon regulatory factor 8 (IRF8) contributes to cell proliferation and leukemogenesis of T‐cell acute lymphoblastic leukemia (T‐ALL) via transcriptional regulation of PIK3R5 and activation of phosphatidylinositol 3‐kinase (PI3K)/AKT pathway." (PMID 36478193, 2023).
adenovirus infection (1 paper, 2022). "The PI3K-AKT signaling pathway (PIK3AP1, PIK3CB, and PIK3R5) is closely related to adenovirus infection and specifically involves mediation of PI3K activation." (PMID 35774982, 2022).
asthma (1 paper, 2021). "The GM13-up related to interleukin-26 (IL26, PIK3R5, and LRRC2) was much higher expressed in severe individuals while the GM12-down module related to the nervous system (10%, p = 1.77E-04, i.e., TUBB2B, SPOCK1, and ASCL1) was much lower expressed in severe asthma individuals." (PMID 34759961, 2021).
colorectal cancer (1 paper, 2016). A primary or metastatic malignant neoplasm that affects the colon or rectum. "Furthermore, the lower expressions of TGF-β and PIK3R5 genes by HF diet may affect the progression of colorectal cancer." (PMID 27161113, 2016).
gestational diabetes mellitus (1 paper, 2020). "First, the potential of PIK3R5 as a clinical biomarker for gestational diabetes mellitus has been confirmed." (PMID 32596376, 2020).
glioma (1 paper, 2022). A benign or malignant brain and spinal cord tumor that arises from glial cells (astrocytes, oligodendrocytes, ependymal cells). "The Macro index comprised of PIK3R5, PIK3R6, ALOX5, ALOX5AP, and ALOX15B serves as a valid prognostic biomarker for gliomas, especially LGG." (PMID 36159811, 2022).
Hepatitis (1 paper, 2013). Inflammation of the liver. "Other downregulated genes after 2-days were pik3r5, akt3a, nfkbiab, hras, mapk14a in hepatitis, pik3r5, akt3a, il1b, il12a, raf1b, map2k1 in influenza and pik3r5, akt3a, nfkbiab, il1b, il12a in measles." (PMID 24069208, 2013).
memory impairment (1 paper, 2018). "The real-time quantitative PCR analysis of the expression of Pik3r5, Il-1β, and Slc18a2 further indicated that these three genes were all the key factors in the effects of Cordyceps polypeptide on the nervous system in the mouse model of learning and memory impairment." (PMID 29736181, 2018).
metastatic melanoma (1 paper, 2012). A melanoma that has spread from its primary site to another anatomic site. "Overall, in metastatic melanoma, the PI3K pathway is altered by somatic mutations in a wide array of genes including PIK3CA, MTOR, PIK3R1, PIK3R5, and IRS4." (PMID 22912864, 2012).
non-small cell lung carcinoma (1 paper, 2017). A group of at least three distinct histological types of lung cancer, including non-small cell squamous cell carcinoma, adenocarcinoma, and large cell carcinoma. "In particular, hypermethylation of PIK3R5, CDKN2A and two retinoid X receptors (RXRG and RXRG) occurred in a non-redundant manner in the non small cell lung cancer subtypes (Z score=2.82, empirical P<0.01)." (PMID 28581523, 2017).
pancreatic cancer (1 paper, 2015). "Pathway analysis of its target genes via DAVID showed enrichment (FDR < 5 %) of genes in the Jak-Stat signaling pathway, including several receptors of interleukins (PTPN6, IL22RA1, CREBBP, IL28RA, IL15RA, PIK3R5, STAT3) and pancreatic cancer pathways (VEGFC, ACVR1B, PIK3R5, EGF, STAT3)." (PMID 26572553, 2015).
SHORT syndrome (1 paper, 2017). A rare disorder characterized by multiple congenital anomalies, including short stature, hyperextensibility of joints, ocular depression, Rieger anomaly and teething delay in which the cause of the disease is a mutation in PIK3R1 gene. "PIK3R5, is a regulatory subunit of the class I phosphatidylinositol 3-kinase (PI3K) gamma complex and it has been shown that mutations in another PI3K regulatory gene subunit, PIK3R1, are responsible for human short syndrome, which is characterized by a variety of symptoms including short stature." (PMID 28454565, 2017).
viral infection (1 paper, 2017). "Interestingly genes RASD1 NEFL, CALCA and PIK3R5 are more involved in cell signalling and proliferation, possibly reflecting the impact of viral infection on cell-cycle." (PMID 28406989, 2017).
cancer (13 papers, 2010 to 2025). A tumor composed of atypical neoplastic, often pleomorphic cells that invade other tissues. "Seven target genes, namely DDX5, SOS2, ACTG1, EZR, FN1, HCLS1 and PIK3R5, were involved in proteoglycans in cancer signaling pathway." (PMID 32293320, 2020). "In the “pathways in cancer”, PIK3R5, SPI1, and CSF1R are most relevant to FPR3 expression (Figures 7A1–A3)." (PMID 33679387, 2020). "In our research, we found that MAPK1, FGFR1, and PIK3R5 participate in more than 4 important cancer-related signaling pathways." (PMID 30560088, 2018). "Moreover, we found downregulation of cancer-associated genes such as BCL2, FLT3LG, or PIK3r5 in cells treated with decitabine." (PMID 27658391, 2016). "We also observed several novel candidate cancer genes, one of which was PIK3R5." (PMID 22912864, 2012). "The degree of methylation of PIK3R5, PIK3R1, MAPK10, and CD40 genes in cancer tissues was significantly increased compared to normal tissue, while most of the remaining genes were reduced." (PMID 37666853, 2023). "This analysis suggested the hypermethylation of TWIST1, CDKN2A (ARF2), PIK3R5 and TBX2 are present in cancers of the breast, colon, lung and prostate." (PMID 33143142, 2020). "A survey of literature suggests the hypermethylation of the associated proteins, including PIK3R5, TBX2 and TWIST1 individually, have multiple biological functions in various cancers, and could serve as potential methylation targets to screen for onset of different cancers." (PMID 33143142, 2020). "Additionally, the detection of hypermethylated PIK3R5, TBX2 and TWIST1 in all four tumor tissues suggests the specificity of these biomarkers for the four TCGA cancers screened in this manuscript, and their potential as therapeutic targets." (PMID 33143142, 2020).
tumor (13 papers, 2018 to 2025). "For instance, higher expression of CD69 and PIK3R5 was associated with enhanced sensitivity of tumor cells toward multiple chemotherapeutics such as nelarabine, fluphenazine, and dexamethasone decadron." (PMID 36497225, 2022). "For example, up-regulated CD69 and PIK3R5 were associated with higher tumor cell sensitivity with various chemotherapeutics like nelarabine, fluphenazine, and dexamethasone decadron." (PMID 36497225, 2022). "Suppressing the expression of PIK3R5 by miRNAs resulted in the promotion of epithelial-mesenchymal transition and oncogenic autophagy by regulating the Akt-mTOR signaling pathway in tumor cells." (PMID 35884407, 2022). "The expression of CCL20, CD70, PCDH7, DCBLD2, and MMP14 genes were remarkably more elevated within LUAD samples than adjacent non-tumorous tissues, where PIK3R5, RNF144B, BTG2, CD69, and MEP1A genes were the opposite." (PMID 36497225, 2022). "Since there is a close association of LPAR1 with the PI3K-Akt signaling pathway, LPAR1 may cooperate with PIK3R5 to exert tumor-suppressing effects, which needs further exploration." (PMID 35884407, 2022). "Using western blot analysis, Transwell assay, wound-healing assay, and 3D spheroid BME cell-invasion assay, the results showed that co-transfection of PIK3R5 in miR-210-5p upregulated OS cells reversed the functional role of miR-210-5p in promoting tumor invasion and migration." (PMID 32024814, 2020). "Mechanistically, collagen XVII promotes the expression of PIK3R5, a subunit of the PI3Kγ complex that activates PI3K/AKT signaling in PDAC, thereby suppressing cell migration and tumor growth." (PMID 40728119, 2025). "Co-expression analysis highlights genes like PIK3R5 (PI3K–AKT signaling), CEBPB (linking inflammation to tumor progression), and STAT2 (JAK–STAT amplification)." (PMID 41303731, 2025). "This requires glucose uptake and energy sources for normal cellular response to stress and tumor growth, syndrome development, vascular changes, and megalocephaly (e.g., PIK3R1; PIK3CA; PIK3CG; PIK3CD; PIK3CB; PIK3R3; PIK3R2; PIK3R5; PIK3R6)." (PMID 41010006, 2025). "The expression level of PIK3R5 was significantly negatively correlated with TNM stage, lung metastasis, and tumor size." (PMID 32024814, 2020). "Indeed, targeting PI3Kγ is even more effective than cytarabine in PIK3R5-elevated AML cells without clear side effects, and eganelisib synergizes with cytarabine to inhibit tumor growth in vivo." (PMID 39507412, 2024).
infection (4 papers, 2013 to 2020). The state of being infected such as from the introduction of a foreign agent such as serum, vaccine, antigenic substance or organism. "Through genetic knockdown approaches, we identified phosphoinositide 3′-kinase γ (PI3Kγ) and its regulatory subunit PIK3R5 as cellular proteins that facilitate infection of human SVG-A glial cells by JCPyV." (PMID 33092168, 2020). "CRISPR/Cas9-mediated knockout of PIK3R5 or PI3Kγ inhibited infection by authentic JCPyV and by JC pseudovirus." (PMID 33092168, 2020). "Here, we surveyed the role of cellular signaling proteins in JCPyV infection and found that shRNA- and siRNA-mediated knockdown of phosphoinositide 3’-kinase (PI3K) γ and the PI3Kγ regulatory subunit 5 (PIK3R5) specifically inhibited infection by JCPyV and JC pseudoviruses." (PMID 33092168, 2020). "Lastly, it is worth noticing that LTNP 006 had two variants potentially affecting HIV nuclear import by the PIK3R5 and MAP1A genes and had undeletable levels of newly integrated HIV DNA post infection, which cannot be attributed to the more common protective alleles in this LTNP." (PMID 30323326, 2018). "Surprisingly, in our study we also observed that more than 18 key genes, including Jak2, Stat3, Stat5a, Pik3r5 and Cish, of JAK-STAT pathway were significantly up-regulated by S. aureus + PG infection, thus indicating that S. aureus + PG treatment might also activate JAK-STAT signaling." (PMID 29304086, 2018).
cardiovascular diseases (1 paper, 2023). "Pik3r5 encodes the catalytic subunits of PI3K signaling pathway which could control AKT/NO/mTOR, NADPH oxidase, and TGF-b/Smad pathway that are involved in cardiovascular diseases." (PMID 37071017, 2023).
PIK3R5 also shares sentences with these, for which no sentence is quoted: lymphoma (3 papers); type 2 diabetes mellitus (2); ataxia telangiectasia (1); Ataxia with vitamin E deficiency (1); Chronic colitis (1); colon cancer (1); diffuse large B-cell lymphoma (1); dysplasia (1); Hyperglycemia (1); Hypertension (1); influenza (1); Insulin resistance (1); lung diseases (1); lymph node metastasis (1); measles (1); pancreatic ductal adenocarcinoma (1); staphylococcus aureus infection (1).